EPCAM (epithelial cell adhesion molecule)
Diseases named in the same sentence as EPCAM in open-access papers (continued):
Sharing a sentence is not in itself a finding about the gene and the disease.
cancer (continued). "To formally prove this hypothesis, we decided to use EpCAM, a common marker found in epithelial carcinomas, in combination with tetraspanins." (PMID 30765839, 2019). "A higher number of EpCAM+ CD4+ T cells are observable in the carcinoma tissue images." (PMID 31354723, 2019). "A very high frequency of EpCAM+ cells was found in all cell lines and a band of 40 kDa was observed upon western blotting for all cell lines, suggesting that these cell lines were fully differentiated carcinoma cells." (PMID 31285270, 2019). "With regard to carcinoma-derived CTCs the most widely used markers are EpCAM or CK." (PMID 31466397, 2019). "EpCAM in turn has been described as a cell adhesion molecule and, more recently, as a signaling membrane protein that regulates cell proliferation and differentiation in cancer and stem cells." (PMID 30261040, 2018). "Therefore, the developed strategy will become a promising and reliable method for the ultrasensitive detection of EpCAM in the early clinical diagnosis of cancers and medical research." (PMID 35541343, 2018). "As the characteristics of the cancer cell membrane depend on its membrane proteins, we identified five major proteins associated with cell invasion and metastasis (CD44, CD47, E-cadherin, EpCAM, and Tissue factor) using western blot." (PMID 30487569, 2018). "Epithelial cell adhesion molecule (EpCAM) is expressed in many types of cancer stem cells." (PMID 30551640, 2018). "Over-expression of EpCAM is also related to cancer radiosensitivity." (PMID 30419852, 2018). "Notably, EpCAM has been selected as a target antigen for various anti-cancer antibody therapeutics, such as adecatumumab, edrecolomab, 3622W94, and ING-1." (PMID 30140380, 2018). "Accordingly, EpCAM has been considered to be a potential therapeutic target to treat cancer." (PMID 28290053, 2018). "Additionally, Epithelial cell adhesion molecule (EpCAM), a cancer stem cell surface marker, is an interesting target with over-expression in many human solid tumors." (PMID 29467932, 2018). "Hence, EpCAM has been considered as a suitable candidate for cancer target therapy via immunotoxins (ITs) development." (PMID 30276141, 2018). "As the PI3K/Akt/mTOR signalling pathway plays a very important role in cancer therapeutic resistance including CaP, we investigated whether this pathway is involved in the effects of EpCAM-KD on CaP xenografts using IHC." (PMID 30419852, 2018). "However, this efficacy was demonstrated only in patients that had a high expression of EpCAM on the cancer cells surface." (PMID 30586898, 2018). "Some lines of evidence suggest that EpCAM is required for the proliferation of cancer stem cells." (PMID 29652830, 2018). "In addition, this approach has been successfully applied in the specific and sensitive detection of EpCAM in real samples, indicating that it will become a reliable method for EpCAM detection in the early clinical diagnosis of cancers." (PMID 35541343, 2018). "Finally, cell migration and motility are attenuated in murine knock-out cells, suggesting that EpCAM plays a role in cancer cell invasion and metastasis, and that, in cancer cells, where EpCAM is over-expressed, it acts as a negative regulator of adhesion." (PMID 29329202, 2018). "EPCAM is a cell surface glycoprotein that serves as a marker of cancer stem cells." (PMID 30186744, 2018). "Hence, EpCAM represents an excellent measure for the level of epithelial differentiation of carcinoma cells in head and neck tumors, whereas vimentin depicts a gradual mesenchymal switch." (PMID 30275505, 2018). "The results of this study could suggest that Ep1 aptamer can bind specifically to the cellular EpCAM protein, making it an attractive ligand for targeted drug delivery and as an imaging agent for the identification of cancer cells." (PMID 29245156, 2017). "Therefore, bispecific antibody targeting EpCAM provides an attractive choice for immunotherapy of those cancers." (PMID 28931402, 2017).
cancer (continued). "Finally, in 2015, Krishnakumar and colleagues described a two-pronged approached to EpCAM inhibition in cancer cells." (PMID 28792479, 2017). "In the future, perhaps sorting for the more abundant EPCAM+ population may improve sensitivity for cancer detection." (PMID 28487492, 2017). "Here, we assessed whether EnAd could be engineered to express and secrete a BiTE from infected cancer cells that would activate T cells to bind and kill EpCAM‐positive target cells." (PMID 28634161, 2017). "Our laboratory has developed the first RNA aptamers that target the cancer stem cell markers EpCAM." (PMID 28724889, 2017). "However, the sensitivities of EpCAM-based detection methods seemed to be significantly lower than EpCAM-independent detection methods due to the down-regulation of EpCAM in cancer cells during epithelial-mesenchymal transition (EMT) process." (PMID 28423562, 2017). "Furthermore, successful transfection of EpCAM overexpression in cancer cells led to upregulation of Bcl-2 expression and downregulation of concomitant Bax expression." (PMID 28574829, 2017). "Immunohistochemical analysis revealed that the staining intensity of EpCAM, and the relative area occupied by EpCAM-positive cancer cells were significantly higher in tumors of patients who received platinum-based chemotherapy than in those of matched patients who did not (P = 0.016)." (PMID 28574829, 2017). "Since our molecular analyses indicated an activation of stemness in the SL region, we next assessed the gene expression levels of specific HCC/differentiation markers (AFP, GPC3, albumin) as well as the selected (cancer-) stemness markers (EpCAM, CD133, CK19) and pluripotency genes (NANOG)." (PMID 28415775, 2017). "Similar to CD44, CD133, and CD166, EpCAM is also considered as a cancer stem cell (CSC) marker." (PMID 28931402, 2017). "An antibody, conjugated to Cy5 fluorophores, raised against EpCAM that is expressed on the cell membranes of most carcinomas, and an antibody conjugated to FITC fluorophores prepared against CD44, another cell membrane protein expressed on tumors of epithelial origin, were used." (PMID 28085924, 2017). "Notably, the key CSC marker CD133 and the epithelial carcinoma marker EpCam were expressed at levels 3- to 10-fold higher in CM-T47D and CM-BT549 cells compared with untreated miPS cells." (PMID 28754894, 2017). "The result suggests the newly-explored coumarin-like compounds may have a safety profile better that warfarin when used as the EpCAM-based anti-adhesion therapy for cancer metastatic prevention." (PMID 27480614, 2016). "On the contrary, EpCAM is a well-established marker for TICs, cancer cells and stem cells." (PMID 27612430, 2016). "Additionally, the CD147+EpCAM+ taMPs were significantly reduced compared to the elevated cancer taMPs values." (PMID 27127176, 2016). "It suggests that relying on EpCAM expression for detection of CTCs could result in a failure to detect many cancer cells that have undergone EMT in the bloodstream in patients." (PMID 27013581, 2016). "However, numerous studies have demonstrated that the EpCAM antibody-based positive selection method is imperfect, as EpCAM expression on cancer cells varies not only from patient to patient but also within the same patient over time." (PMID 27501846, 2016). "Therefore we used Caco-2 (CD133+, EpCAM+) and HT-29 (CD133−, EpCAM+) targets and performed the assay with freshly isolated NK cells of two donors for each cancer cell line and (3C, 3D) respectively." (PMID 27650544, 2016). "In order to analyse whether EpCAM might get lost during NSCLC cancer progression, EpCAM protein expression was investigated in primary lung tumours (n = 55) as well as brain metastases (n = 76) by IHC." (PMID 27302574, 2016).
cancer (continued). "Further, effectiveness of bLf-Dox conjugates against drug resistant CD44+/EpCAM+ double positive cancer stem cell enriched DU145 cells was tested, which showed that both Apo-bLf-Dox and Fe-bLf-Dox were capable of inhibiting clonogenic, migration as well as 3D growth properties of these cells." (PMID 27576789, 2016). "In addition, a previous study in mice demonstrated the presence of EpCAM+ bone marrow-derived mesenchymal stem cells with expression of epithelial phenotypic markers, suggesting that detection of EpCAM+ non-cancer cells is possible in the peripheral blood." (PMID 26897248, 2016). "This study has identified 32 proteins associated with CD9 including a protein complex between CD9 and epithelial cell adhesion molecule (EpCAM); (iii) a recent study has demonstrated a knock-in AP-MS approach using epitope-tagging of endogenous genes in cancer cells." (PMID 27011181, 2016). "The mechanisms regulating EpCAM gene expression in cancer are not fully understood." (PMID 27431859, 2016). "Taken together, EpCAM+CD147+ double positive taMPs could potentially serve as novel promising clinical parameter for cancer screening, diagnosis, surveillance and therapy monitoring." (PMID 27127176, 2016). "Furthermore, acute inflammation was stimulated by trigger such as caerulein in vivo, which resulted in increased fluorescent signal of the cy5.5-EpCAM/muc1 ALB during cancer metastasis due to exogenous expression of EpCAM/muc1 in Panc02-implanted mouse model." (PMID 27886058, 2016). "Further characterization of CTCs, including low-EpCAM populations, using this technology may improve detection techniques and cancer diagnosis, ultimately improving cancer treatment." (PMID 27013581, 2016). "Interestingly, those types of pluripotent stem cells tend to express epithelial markers such as epithelial cell adhesion molecule (EPCAM) or E-Cadherin, which is in contrast with the so-called cancer stem cells that are associated with a mesenchymal phenotype." (PMID 26908442, 2016). "The results from the analysis of serum and tissues encouraged us to further analyze the histological distributions of FGF19 and its receptor FGFR4 as well as EpCAM, a potential cancer stem cell marker, corresponding to the clinical histological stages, including ST, NASH, CR and HCC." (PMID 27447573, 2016). "In a first step, we analysed EpCAM expression in primary lung tumours as well as brain metastases, in order to investigate whether EpCAM might get lost during NSCLC cancer progression." (PMID 27302574, 2016). "In addition to PLGA, a polyethylenimine (PEI)-based noncomplex that employs the EpCAM aptamer and EpCAM siRNA was developed for siRNA delivery to EpCAM positive cancer cells." (PMID 27827876, 2016). "Many of the more common assays employ a positive selection strategy, utilizing ferromagnetic particle bound anti-EpCAM antibodies to select epithelial CTCs, based on the assumption that carcinoma cells typically express epithelial markers while white blood cells (WBCs) in the blood do not." (PMID 27634877, 2016). "Furthermore, high levels of EpCAM expression correlate with increased tumorigenesis in various carcinomas." (PMID 27240402, 2016). "Based on our bispecific NK cell engager platform we constructed a tetraspecific killer engager (TetraKE) comprising single-chain variable fragments (scFvs) binding FcγRIII (CD16) on NK cells, EpCAM on carcinoma cells and CD133 on cancer stem cells in order to promote ADCC." (PMID 27650544, 2016). "EpCAM is a frequently expressed marker on carcinoma cells that has impact on patient prognosis." (PMID 27650544, 2016). "This nanocomplex exhibited decreased cell proliferation than the scrambled aptamer loaded nanocomplex in the EpCAM expressing cancer cells and may have potential for EpCAM targeting in vivo." (PMID 25576037, 2015).
cancer (continued). "This hypothesis is supported by several studies that have reported that catumaxomab (anti-EpCAM × anti-CD3 antibodies) shows convincing therapeutic efficacy in patients with malignant tumors." (PMID 25880692, 2015). "EpCAM is expressed in many human cancers with an epithelial origin." (PMID 26540343, 2015). "Because increased intracellular NO synthesis is also aproperty of cancer-progenitor cell-like features, the expression levels of HCCcancer-progenitor cell markers, such as EpCAM and CD13 were examined, which were significantly increased inmiR122-silenced cells." (PMID 25826076, 2015). "The role of EpCAM in cancer research has been covered in numerous articles and is beyond the scope of this review; therefore, we will only touch on the insights garnered from work of EpCAM in cancer." (PMID 25477371, 2015). "One possible reason for the enhanced glycosylation of EpCAM in cancers might relate to the positive impact of glycosylation on the molecule's retention time at the membrane." (PMID 25477371, 2015). "EpCAM-specific antibodies were designed and used to treat many cancers in vitro and in vivo." (PMID 25960617, 2015). "In normal cells, this full length EpCAM protein is sequestered in tight junctions and therefore less accessible to antibodies, whereas in cancer cells it is homogeneously distributed on the cancer cell surface and has been explored as a surface-binding site for therapeutic antibodies." (PMID 25695234, 2015). "Stably transfected, human EpCAM-expressing CHO cells were characterized for expression levels of human immune evasion proteins in comparison to natural levels found in six human cancer cell lines A549 (lung), BxPC3 (prostate), KATOIII (gastric), SKBR3 (breast), SW480 (colorectal), and A431 (skin)." (PMID 26510188, 2015). "The universally recognized markers of CTCs are the epithelial specificities, CD326 (EpCAM) and the cytokeratins, however, recent findings have highlighted the complex nature of cancer cell dissemination, which involves deep cell changes, including the epithelial-to-mesenchymal (EMT) transition." (PMID 25624884, 2015). "Owing to the frequent deregulation of the Wnt pathway in cancer cells and to its functions in progenitor cells, a concomitant upregulation of EpCAM in these cell types may possibly be mediated by the Wnt pathway." (PMID 25477371, 2015). "The cancer cells of a part of these patients might shed soluble EpEX or full-length EpCAM in the ascitic fluid reflecting probably a particularly aggressive disease course that is no more revertible by catumaxomab." (PMID 26296970, 2015). "In addition, we further investigated the colocalization between ALDH1A1 and several cancer stem/progenitor markers (EpCAM, BMI1, CD13, CD24, CD90 and CD133) which have discovered recently to evaluate “stemness” in ALDH1A1-overexpressing cells in this report." (PMID 26160842, 2015). "EpCAM, a luminal epithelial marker, was used to distinguish cancer nests and stromal region." (PMID 26284927, 2015). "Together, these results strongly suggest a significant role for EpCAM in human cancer progression." (PMID 26356670, 2015). "While EpCAM was high expressed in the cancer cells and was considered as oncogene." (PMID 26356670, 2015). "All these investigations have increased the promise of EpCAM as a target for cancer therapy." (PMID 25960617, 2015). "Collectively, these results suggest that EpAb2-6 may induce cancer cell cytotoxic activity by inducing an apoptosis pathway, and that EpAb2-6 inhibits EpICD nuclear translocation by blocking the cleavage of EpCAM." (PMID 26317650, 2015). "The immunotoxin could bind to EpCAM in carcinoma cells, but whether it was cytotoxic to cancer cells requires more study." (PMID 25960617, 2015).
cancer (continued). "Up- and down-regulated genes in all three putative CSCs (A549 CD166+/CD44+, A549 CD166+/EpCAM+, and H2170 CD166+/EpCAM+) were found to be involved in several biological cancer processes, including angiogenesis, apoptosis, anti-apoptosis, induction of apoptosis, cell death, and cell migration." (PMID 25881239, 2015). "In our series, the co-expression of γSMA and EpCAM, together with the down-regulation of E-cadherin, is consistent with the paradigm that cancer stem-like cells might arise from cancer cells via an EMT process." (PMID 26110787, 2015). "It is possible that with a better understanding of EpCAM and its function in cancer cells and CSCs, a component of EpCAM signaling may be identified that will provide a better and more specific target for cancer therapy." (PMID 25636521, 2015). "The present study demonstrates that EpCAM may be a promising target antigen for the development of cancer therapy." (PMID 26317650, 2015). "Therefore, we propose that EpCAM is required for cell migration and cancer invasion and metastasis and required controlled degradation of the extracellular matrix (ECM)." (PMID 26356670, 2015). "Epithelial cell adhesion molecule (EpCAM) has been widely explored as an epithelial cancer antigen." (PMID 25695234, 2015). "EpCAM gene expression has been observed in cancer cells of approximately 75% of patients with malignant ascites and therefore, the EpCAM-targeting antibody catumaxomab was approved in 2009 by the European Union for the intraperitoneal treatment of patients suffering from malignant ascites." (PMID 25947366, 2015). "EpCAM expression has been reported in a number of different carcinomas." (PMID 26474755, 2015). "EpCAM is an epithelial cell marker overexpressed in carcinomas of various origins." (PMID 26314961, 2015). "Furthermore, due to the prevalence of EpCAM on many carcinomas, it has been (re)discovered many times and has been ascribed >20 different names." (PMID 25477371, 2015). "Normal epithelia express EpCAM at a variable but generally lower level than carcinoma cells." (PMID 25477371, 2015). "In addition, an EpCAM/CD16 bi-specific scFv antibody fragment showed enhanced in vitro killing of human carcinomas with a broad range of origins, as well as efficient killing of NK-resistant carcinoma targets." (PMID 26284063, 2015). "EpCAM is a transmembrane glycoprotein, which is primarily expressed in simple epithelia, progenitor cells, normal and malignant stem cells, as well as in numerous carcinomas of different origin." (PMID 25477371, 2015). "Thus, growing evidence indicates that the role of EpCAM in cancer should be further investigated in light of its interaction with these molecules." (PMID 24727741, 2014). "It was, however, unclear whether all the human cells (i.e. all cancer cells) in the cell suspension were detected using EpCAM, and furthermore, whether the antibody also recognized the mouse version of the antigen." (PMID 25419568, 2014). "Our data indicate that targeted methylation of the EpCAM promoter could be an approach in the therapy of EpCAM overexpressing cancers." (PMID 24489952, 2014). "The significance of the presence and identification of EpCAM in cancers depends on the cancer type." (PMID 23959111, 2014). "Recently, it has been suggested that EpCAM is a cancer stem cell marker and may be expressed by cells undergoing epithelial to mesenchymal transition (EMT), lacking other epithelial markers." (PMID 24528603, 2014). "Epithelial derived cancers account for 80–90% of malignancies, and it has been observed that CTCs found in patients with solid epithelial tumors express epithelial markers such as the epithelial cell adhesion molecule (EpCAM) and cytokeratin (CK)." (PMID 24489774, 2014). "The IRS of cancer cells with membranous EpCAM expression ranged from 0 to 12 (median 7.3)." (PMID 25240521, 2014).